BRAF (B-Raf proto-oncogene, serine/threonine kinase)
Diseases named in the same sentence as BRAF in open-access papers (continued):
Sharing a sentence is not in itself a finding about the gene and the disease.
melanoma (continued). "Another study tested the impact of blocking the ABCB5 transporter on recurrent melanoma, but found that knockdown of ABCB5 did not re-sensitize BRAF inhibitor-resistant melanoma cell lines, in spite of the fact that ABCB5 is highly expressed in malignant melanoma-initiating cells." (PMID 35048028, 2021). "The lack of confirmed objective responses in BRAF mutant CRC, in contradistinction to melanoma, to the RAF dimer inhibitor lifirafenib which inhibits all RAF isoforms as well as EGFR and KRAS supports this hypothesis." (PMID 32922659, 2020). "Remarkably, BRAF inhibition induced only a moderate decrease in expression of sterol regulatory element-binding protein-1 (SREBP-1), a master regulator of lipid metabolism, and did not significantly affect lipogenesis in therapy-resistant melanoma cells." (PMID 31910904, 2020). "Inhibition of MCL-1 through miR-32 may be an effective anti-melanoma strategy, regardless of the status of NRAS, BRAF or PTEN, as MCL-1 inhibition exhibits synergistic effects with Vemurafenib." (PMID 32054078, 2020). "First, the combination of CK2 inhibitors with other drugs might not be convenient: in melanoma and thyroid carcinoma with wt BRAF, the effect of CK2 inhibition in combination with vemurafenib or selumetinib (BRAF/MEK inhibitors) was poor or even antagonistic." (PMID 31277672, 2019). "Furthermore, in a significant proportion of BRAF mutant cases metastases switched from low to high or high to low MAF and such an extreme shift also occurred individually in heterogeneous multiple metastatic BRAF mutant cases, unlike in NRAS mutant melanomas." (PMID 31391014, 2019). "TTM was not toxic against V600E-mut-BRAF A375 and G12D-mut-KRAS/high c-myc C8161 melanoma cells." (PMID 30792807, 2019). "Importantly, as shown in our study, BRAF/MEK/CDK4/6 inhibition produced sustained and durable response in BRAFV600E-mutant melanoma patient-derived preclinical models regardless of drug sensitivity." (PMID 29541385, 2018). "Since they are known to be moderately sensitive to BRAF and MEK inhibitors, their presence at such a high rate in our population prompted us to perform a more comprehensive sequencing of “pan-negative” melanoma samples." (PMID 30546839, 2018). "Common genomic subtypes of human cutaneous melanoma (BRAF, RAS (N/H/K), and NF1 in 90% of cases) that engage oncogenic signaling through the MAPK pathway are less common in human non-cutaneous melanoma and in canine malignant melanoma (24% of cases here)." (PMID 30188888, 2018). "Additionally, a large subset of melanoma utilizes OXPHOS in their metabolism, which can confer de novo resistance to BRAF inhibitors." (PMID 30651927, 2018). "Interestingly, resistant colonies emerged in the absence of BRAF and CRAF expression following tamoxifen treatment of melanoma cell cultures." (PMID 28497782, 2017). "Moreover, there are no effective treatment options available for wildtype BRAF/NRAS melanomas, which constitute ~30% of all melanomas." (PMID 27846237, 2016). "Furthermore, based on previous experience with BRAF and MEK inhibitors, it is plausible that not all BRAF-V600E melanomas are uniformly sensitive to ERK inhibition; hence, it is important to identify molecular markers associated with response and resistance." (PMID 27655717, 2016). "In our patient, after six weeks of treatment with BRAF/MEKi, an increase in CD8+ PD-L1+ lymphocyte infiltration was found at the cutaneous primary melanoma in complete regression, whereas there was no infiltration by CD8+ cells on bone metastases biopsy performed two weeks after starting BRAF/MEKi." (PMID 27447748, 2016). "These melanoma cells were highly sensitive to CRAF, but not BRAF knockdown." (PMID 27273450, 2016). "We here identify miR-32/MCL-1 pathway members as key early genetic events driving melanoma progression, and suggest that their inhibition may be an effective anti-melanoma strategy irrespective of NRAS, BRAF, and PTEN status." (PMID 27846237, 2016).
melanoma (continued). "Certainly, this approach is not applicable for those with wild-type BRAF melanoma, but for those with the BRAF-mutant LMD, we hope that our case will spark the interest in well-designed studies to evaluate BRAF inhibitor-based therapy with or without radiation therapy." (PMID 25962795, 2015). "In total, only 9.6% of all cases in the cohort were negative for either of the genetic changes in BRAF, NRAS, NF1 and KIT, indicating that the majority of melanomas could potentially have activated MAPK pathway through these genetic alterations." (PMID 25909218, 2015). "However, BRAF inhibition is not effective in the remaining 50% of BRAF wild-type melanoma, including NRASQ61 melanoma." (PMID 25142146, 2014). "In melanoma cell lines, which have acquired resistance to the RAF inhibitor, elevated CRAF protein levels accounted for the acquisition of resistance to RAF inhibitor, and CRAF, but not BRAF activated the MEK/ERK pathway." (PMID 25422890, 2014). "This indicates that combination of selective BRAF inhibitors with ABT-737 or ABT-263 may increase the degree and rate of responses in previously untreated patients with V600E melanoma but not in those with acquired resistance to these agents." (PMID 26556430, 2014). "Indeed, there is little information linking miRNAs to the MAPK/ERK signaling pathway, and there is no published evidence for miRNAs directly targeting BRAF, MEK, or ERK, the main components of the MAPK/ERK pathway in melanoma." (PMID 25275294, 2014). "Consequently, it is not surprising to find that only 23% of BRAF V600E-positive nevi have detectable levels of ERK, while 93% of BRAF V600E-positive melanomas have detectable levels of ERK." (PMID 22363855, 2011). "Inhibition of mutated BRAF using new specific BRAF inhibitors is reported in 2009 (ASCO) to be effective so that whether BRAF is a prognostic marker or not, BRAF driven MAPK pathway activation clearly drives tumor growth in melanoma tumors." (PMID 20140953, 2010). "We selected these lines because mutant BRAF is highly sensitive to Hsp90 inhibition although melanoma cells regardless of their BRAF status are also growth inhibited by agents such as 17-AAG, most likely because of depletion of CRAF as well as BRAF, in addition to effects on other client proteins." (PMID 21037799, 2010). "Importantly, we show that wild type BRAF does not induce BRN2 expression in melanocytes, and neither does it stimulate MITF transcription in melanocytes or melanoma cells." (PMID 18628967, 2008). "In the context of BRAF-mutant melanoma, the persistent activation of the MAPK signaling pathway not only augments cellular proliferation but also disrupts cell death signaling by upregulating the anti-apoptotic protein Mcl-1, ultimately resulting in resistance to BRAF inhibitors." (PMID 40331942, 2025). "Moreover, the GSDME protein levels in cancer cells are not as invariable as those in normal cells, and BRAF/MEK inhibitors can promote the cleavage of GSDME and the release of high-mobility group box 1 (HMGB1), which are markers of pyroptotic cell death in melanoma cells." (PMID 38336727, 2024). "Altogether, we retrospectively analyzed 138 stage III melanoma patients who were diagnosed with microscopic SLN metastasis at the skin cancer center of the University Hospital Cologne between 2011 and 2020 and who did not receive prior adjuvant therapy with ICI or BRAF/MEK-inhibitors." (PMID 36765660, 2023). "However, in subsequent studies, IHC detection of stromal or tumor HGF in pre-therapy melanoma specimens failed to predict patient response to BRAF inhibitors; therefore, the power of HGF as a negative predictor of response to BRAF-targeted therapies needs to be further investigated." (PMID 36324182, 2022).
melanoma (continued). "Interestingly, BRAF, NF1 and RAS were not significantly differentially methylated in melanoma tissues in relation to UV exposure, highlighting that UV exposure produces DNA methylation changes in genes that can be different from critical ones mutationally altered by the same environmental exposure." (PMID 35840550, 2022). "However, our investigation demonstrates that CDK4/6 inhibition does not significantly alter the effects of BRAF and MEK inhibitors on either glycolysis or OXPHOS in melanoma cells, nor does it significantly alter the expression of the MITF-PGC1A-mitochondrial metabolism pathway." (PMID 33572972, 2021). "Moreover, unlike the other BRAF inhibitors, this modality could trigger cellular senescence in BRAFV600E melanoma cells." (PMID 33474634, 2021). "Clinical application of targeted therapy (BRAF inhibitors with or without MEK inhibitors) and immunotherapy (PD-1 inhibitors and CTLA-4 inhibitors) improve the survival of patients with unresectable melanoma, but the principal therapy for localized melanoma is surgical eradication." (PMID 32708762, 2020). "It was proposed that tumors innately resistant to anti-PD-1 therapy share a transcriptional signature with melanoma cells treated with MAPK inhibitors; however, it is not yet known whether a shared phenotype predicting sensitivity to BRAF inhibitors and anti-PD-1 agents exists." (PMID 30925943, 2019). "As oncogenic drivers, one would expect that the primary tumors are dominated by tumor cell clones carrying the activating mutation, however, there are data indicating that this is not necessarily the case; heterogeneity both for mutant BRAF and NRAS may occur in primary melanomas." (PMID 31391014, 2019). "However, clinical responses to BRAF and MEK inhibitors are often not durable due to acquisition of resistance after treatment, highlighting the need to identify novel melanoma vulnerabilities that could be exploited for new treatments." (PMID 31399133, 2019). "Even at 1 μM concentration, both SR4 and niclosamide almost completely inhibited colony formation of all seven melanoma cells after 10 days incubation with the compounds, whereas vemurafenib displayed variable effects on BRAFV600E mutants and failed to inhibit colony growth of wild type BRAF cells." (PMID 30651927, 2018). "However, in contrast to what we observed in A375 cells, A375‐T cells were not able to protect A375‐shEDNRB cells from BRAF inhibition, indicating that EDNRB‐mediated signalling plays an important role in paracrine protection to MAPK pathway inhibition in melanoma cells." (PMID 28606996, 2017). "Importantly, the potential use of such predictive biomarkers would fit into current clinical paradigms because, after the introduction of checkpoint- and BRAF- inhibitors, ACT is no longer considered as a first line therapy in melanoma because of toxicity and complexity." (PMID 29170503, 2017). "In contrast with what is observed in established control melanoma cells, NRAS/CRAF complexes were strikingly much less abundant than NRAS/BRAF complexes in melanocytes at P10, thus explaining why CRAF can compensate for BRAF absence in melanoma cells but not in early melanocytic lesions." (PMID 28497782, 2017). "However, not all BRAF-V600E melanomas respond to these drugs equally; we found that the PI3K and Notch pathways were differentially activated in responder vs. non-responder melanomas." (PMID 27655717, 2016). "Finally, the tissue-specific context of oncogene mutations is clearly critical in determining sensitivity to targeted therapies; notably, single-agent BRAF inhibitors or combination of BRAF and MEK inhibitors are effective inBRAF-mutant melanomas, while they are not effective in BRAF-mutant CRCs." (PMID 27167191, 2016). "Moreover, our data suggest that their inhibition may be an effective anti-melanoma strategy, irrespective of the status of NRAS, BRAF or PTEN." (PMID 27846237, 2016).
melanoma (continued). "The effect of MEK (MAPK/ERK Kinase) inhibition in BRAF mutant NSCLC has not been thoroughly investigated and a recent study showed that the combination of a BRAF inhibitor (dabrafenib) and MEK inhibitor (trametinib) was also effective in treating advanced melanoma." (PMID 25706985, 2015). "However, it will be important to determine whether these are the only mechanisms responsible for the role of TBX3 in melanomas and whether AKT3 can lead to an increase in TBX3 levels regardless of BRAF status." (PMID 25595898, 2015). "A recent study on resistance to an analog of vemurafinib, PLX4720, suggested that only in cell lines with PTEN deletion p-AKT is induced by this BRAF inhibitor, and lack of PTEN may play a role in preventing apoptosis of melanoma cell treated with this compound." (PMID 22194965, 2011). "However, we could not demonstrate co-immunoprecipitation of endogenous BRAF with RAF1, or transiently transfected MYC and FLAG tagged RAF1 in PLX4032-treated melanoma cells under conditions in which RAF1 was activated by the drug." (PMID 20149136, 2010). "Therefore, the aim of this study was to evaluate NFAT expression and activity in metastatic melanoma and establish whether or not oncogenic BRAF signalling modulates NFAT activity and determine if NFAT is a key upstream regulator of COX-2 in melanoma." (PMID 19724275, 2009). "However, as previously highlighted, early trials using BRAF inhibitors as monotherapy in BRAF p.V600E-mutant metastatic mCRC yielded limited clinical benefit, primarily due to rapid feedback reactivation of EGFR and sustained MAPK signaling, mechanisms that are absent in melanoma." (PMID 41153346, 2025). "Moreover, although we previously showed that ICI efficacy in advanced melanoma patients with autoimmune disease (AID) was not inferior, ICI is usually avoided in patients with AID in the adjuvant setting, especially when there is the alternative option of BRAF/MEK-inhibition." (PMID 36672358, 2023). "However, the initial effect of BRAF inhibitors is usually not cytotoxic but cytostatic (i.e., G1 cell arrest) since the accumulation of pro-apoptotic BH3-only proteins is neutralized by the abundant amounts of anti-apoptotic proteins usually expressed by melanoma cells." (PMID 33396645, 2020). "Furthermore, the recent development of BRAF inhibitors that do not trans-activate MAPK signalling termed ‘paradox-breakers' may synergise with C012 and could offer a combination therapy purposed for BRAFWT melanomas." (PMID 27447557, 2016). "Finally, we wanted to test, whether BRAF status (BRAF V600E IHC positive or BRAF V600E negative), in combination with clinical features (Breslow ≥ 2mm or <2mm and mitotic count ≥ 1/mm2 or <1/mm2) predicts SNB status and survival in the superficially spreading melanomas." (PMID 31039200, 2019).
colorectal cancer (1,512 papers, 2005 to 2026). A primary or metastatic malignant neoplasm that affects the colon or rectum. "This case highlights the potential for conversion surgery in stage IV BRAF-mutated colorectal cancer with NEC." (PMID 41647691, 2026). "Their findings revealed that a higher total vitamin C intake was significantly associated with reduced colorectal cancer-specific mortality in patients with KRAS or BRAF mutations, compared with those with wild-type tumors." (PMID 41403402, 2026). "Valine to glutamate substitution at residue 600 of the BRAF oncogene (V600EBRAF mutation) is prevalent in human colorectal cancers with a serrated histopathology and is thought to be a founder mutation." (PMID 41790744, 2026). "We identified current optimal first line and later line therapeutic strategies for BRAF-mutated colorectal cancer while guiding future trial design by prioritising high value combination approaches based on comparative effectiveness and safety profiles." (PMID 41355781, 2025). "BRAF V600E mutations, for example, occur in about 8%–10% of colorectal cancer patients and are usually associated with a poorer prognosis and higher levels of aggressiveness." (PMID 40083375, 2025). "This study looked back at 406 patients with BRAF-mutated colorectal cancer to better understand how different types of BRAF mutations and other genetic changes affect how the disease behaves and responds to treatment." (PMID 41002577, 2025). "The approval of anti-EGFR/BRAF regimens for second line treatment of BRAF-mutated colorectal cancer underscores its clinical significance." (PMID 41355781, 2025). "Mutations leading to a defective ZNRF3 protein were identified in several tumor types, but most frequently in colorectal cancers enriched for a mismatch repair defect, BRAF-V600E mutation and right-sided tumor location." (PMID 39674817, 2025). "Concurrently, patients with colorectal cancer harboring BRAF mutations typically exhibit a poor prognosis, and diabetes further elevates the risk of such mutations." (PMID 39926430, 2025). "Research has indicated that diabetes appears to elevate the risk of BRAF mutations in patients with colorectal cancer, a condition typically associated with a poor prognosis." (PMID 39926430, 2025). "In colorectal cancer, about 10%-20% of patients carry BRAF mutations, which are usually associated with strong invasiveness and poor prognosis." (PMID 40959083, 2025). "To elucidate the role of the BRAF V600E mutation in shaping TME of colorectal cancer, we independently analyzed TCGA and GEO datasets using multiple immune infiltration algorithms." (PMID 39934467, 2025). "BRAF-V600E-mutated metastatic colorectal cancer represents a distinct clinical and pathological entity compared to wild-type colorectal cancer, defining a specific subgroup." (PMID 41440935, 2025). "BRAF mutations are rarely detected in patients with oligometastatic colorectal cancer, potentially associated with aggressive tumor behavior." (PMID 41294701, 2025). "In colorectal cancer, these mutations are linked to higher survival post treatment, which distinguishes them from Class I BRAF mutations, associated with poor prognosis." (PMID 40977811, 2025). "This study provides a well-described, real-world cohort of 406 patients with BRAF-mutated colorectal cancer." (PMID 41002577, 2025). "The most common BRAF mutation is the V600E substitution, accounting for about 80% of all BRAF mutations in colorectal cancer." (PMID 41002577, 2025). "Mutations in KRAS and BRAF genes are prevalent in colorectal cancer (CRC), which strikingly promote tumorigenesis and lead to poor response to a variety of treatments including immunotherapy by activating the MAPK/ERK pathway." (PMID 40001243, 2025).